CCL5 (C-C motif chemokine ligand 5)
Diseases named in the same sentence as CCL5 in open-access papers (continued):
Sharing a sentence is not in itself a finding about the gene and the disease.
infection (continued). "Similarly, proinflammatory cytokines CCL2, CXCL10, and CCL5, etc., were markedly elevated in the infection group." (PMID 41090515, 2026). "In addition to type I IFNs, mRNA expression of proteins related to antiviral responses, such as CXCL10, IFIT1, and CCL5, are upregulated after infection." (PMID 39601535, 2025). "CCL5 plays a crucial role in the immune response against M. tuberculosis, particularly in enhancing the immune response by recruiting monocytes to the site of infection." (PMID 40162798, 2025). "Macrophage Inflammatory Protein-1 alpha (MIP-1α), Macrophage Inflammatory Protein-1 gamma (MIP-1γ), and RANTES (CCL5) are chemokines that function to attract immune cells to sites of inflammation or infection, and the levels of these were also elevated by the L-30 extract compared to the control." (PMID 39996816, 2025). "Ccl5/Rantes transcriptional induction occurred early after infection, with a 4.11-fold increase at 3 dpi (SD ± 1.29, p = 0.0007), a 9.08-fold increase at 6 dpi (SD ± 4.64, p = 0.0046), followed by a massive peak at 9 dpi (2,032.2-fold, SD ± 1,129.26, p = 0.0038)." (PMID 41362627, 2025). "Notably, cytokine family members Ccl2, Ccl3, Ccl4, Ccl5, Ccl7, Ccl9, and Ccl22 were also significantly activated following infection." (PMID 40539063, 2025). "The treatment of HIV-infected macrophages with P3DEX significantly increased the production of MIP-1α (84.48 ± 22 vs. 155 ± 40.4 pg/mL; p = 0.03), MIP-1β (208.14 ± 112 vs. 319.9 ± 131.2 pg/mL; p = 0.02), and CCL-5 (125.6 ± 26.54 vs. 198.53 ± 30.9 pg/mL; p = 0.02) 24 h post infection." (PMID 40077760, 2025). "Furthermore, infection led to an increase in the expression of cancer progression-related chemokines Ccl5 and Cxcl16, being upregulated most prominently by SFV/TNFα and SFV/IFNγ." (PMID 40547518, 2025). "Knockdown of Snhg15 during VEEV TC-83 infection resulted in the suppression of ten genes including Irf1, Junb, Atf3, Relb, Pim1, Hbegf, Ccl5, Ankrd33b, and H2-K2, all of which were also increased during TC-83 infection when the expression of Snhg15 increased in primary mouse astrocytes." (PMID 40463150, 2025). "Additionally, chemokines such as CCL3 (MIP-1α), CCL4 (MIP-1β), and CCL5 (RANTES) aid in the recruitment of other immune cells to the site of infection." (PMID 40665369, 2025). "The three most upregulated chemokines during infection were Ccl5, Cxcl9, and Cxcl10." (PMID 40635167, 2025). "Indeed, VSVΔ51 infection induced a large cross-section of antiviral genes (IFITs, IFITMs, OASs, ISGs) and different pro-inflammatory cytokines and chemokines (CCL5, CXCL10, IFNB1) that were all downregulated by 4-OI treatment." (PMID 38750019, 2024). "Having seen that the addition of chemokines over 3 days during the peak of T cell recruitment altered the response to RSV infection and protection against secondary re-infection, we explored if a single dose of CCL5 or CXCL10 on day 7 after infection would be sufficient to enhance TRM recruitment." (PMID 39749186, 2024). "Furthermore, we observed a significant increase in TNFα, IL-1α, IL-2, IL-3, IL-4, IL-9, IL-10, IL-12 (P70), IL-17A, and CCL5 on day 4 post-infection in murine macrophages." (PMID 39038037, 2024). "Additionally, it is known that genetic polymorphisms in the HIV-1 coreceptors (such as in CCR5) and their ligands (like RANTES/CCL5) affect several aspects in immune response, including the severity of the infection." (PMID 38674726, 2024). "The LPS-induced change in CCL5 gene expression from up to downregulation was observed in the FT group, potentially reflecting lower egress of lymphocytes from blood to tissue and consequently a lower immune response of this group to infection due to ageing." (PMID 39272988, 2024). "CCL5 (also known as RANTES) plays a pivotal role in the host immune response by attracting monocytes and T cells to the site of infection, which may contribute to RSV control." (PMID 39403383, 2024).
infection (continued). "Other T cell populations and NK cells were also found to express both Ccl4 and Ccl5 upon infection." (PMID 38236930, 2024). "After 14 days of infection, there were 257 genes with greater expression in nociceptor-ablated mice (e.g., Vegfa, IL1a, IL1b, and Tnf) compared to 219 genes with greater expression in control mice (e.g., Alox5, Car2, Ccl5, Elane, and Mmp8)." (PMID 37845223, 2023). "Infection with virulent ASFV isolates often results in an exacerbated immune response, associated with elevated serum levels of pro-inflammatory cytokines (IL-1α, IL-1β, IL-6, TNF, CCL2, CCL5 and CXCL10)." (PMID 36680273, 2023). "Most cells of both genotypes upregulate CCL5 after infection, which may also interact with the receptor CCR5 present on microglia from both WT and Ifnar–/–." (PMID 37037810, 2023). "Overexpression of CCL5 may reduce the neurotoxicity induced by the infection of HIV, which was related to p38-MAPK and PI3K/Akt pathway." (PMID 36967827, 2023). "Moreover, slightly higher levels of expression were observed in CCL5 during the infection with the mutant virus." (PMID 37513744, 2023). "In contrast, some paired ligands and receptors, such as ANXA1_FPR1, C5AR1_RPS19, CCL5_CCR1, and PTPRC_MRC1, were significantly activated after infection, which may mediate the communication among T cells and myeloid cells." (PMID 37087411, 2023). "Notably, CXCL8 and CCL20 are induced early during vaginal SIV infection in macaques followed by secondary inflammatory process likely driven by CCL5 and other CK-producing cells, leading to recruitment of immune cells and fueling infection." (PMID 35051209, 2022). "Together, these data suggest that ferrets infected with a high dose of M. tuberculosis mount stronger pro-inflammatory responses in the lungs in the form of elevated expression of the genes for IL-6, IL-17, CXCL10, IFN-γ, and CCL5, as compared to the medium and low-dose infection groups." (PMID 36051240, 2022). "In addition to CXCL10 and IFN-γ, the mRNA levels of the CCL5 gene also increased in the high-dose group at 4 weeks post-infection (20-fold) and remained at the same level at 7 weeks." (PMID 36051240, 2022). "Our previous study, comparing acute, primary mCMV infection in MC-competent C57BL/6 (B6) wild-type mice and MC-deficient mutants C57BL/6 (B6)-KitW-sh/W-sh (briefly sash mutants), showed a strong MC-dependent wave of serum CCL-5 peaking on day two, post-infection." (PMID 35563708, 2022). "Ccl5 transcript levels were low 2 h post-infection and increased 4 and 8 h after infection." (PMID 35806257, 2022). "From the results, we observed that most of the chemotactic factors (e.g., CCR5, CXCR6, and CCL5), which are pivotal mediators of host defense and orchestrate the recruitment of immune cells into sites of infection and inflammation, were significantly up-regulated in the IMMUNITY_H samples." (PMID 35359451, 2022). "CCL5 is a pleiotropic chemokine that promotes the recruitment, proliferation, and activation of antigen-specific T cells such as CTLs and has been identified as a critical therapeutic target for a variety of infections." (PMID 35677043, 2022). "CCL5 is one of the key chemokines, that regulate migration of NK cells to the site of infection." (PMID 34516566, 2021). "Taken together, these results suggest a role for eosinophils and the sustained production of CCL5 in the immune response towards PbA-infection in Ifnar1-/- mice that may contribute to ECM protection." (PMID 34659202, 2021). "Upon SeV or EMCV infection, macrophages or MEFs with the deficiency of USP18 showed impaired phosphorylation of TBK1 and IRF3, expression of Ifnb and Ccl5, and production of IFN-β, indicating that USP18 plays a positive role in regulating viral-induced type-I interferon response." (PMID 34016972, 2021). "Similarly, CCL5 plays an important role in the infiltration of NK cells to the site of infection and augments NK cell cytotoxicity and IFN-γ production." (PMID 34516566, 2021).
infection (continued). "We found that many cytokines messenger RNAs (mRNAs), including Il1b, Il5, Il6, Il10, Il12a/Il12p70, Ifng, Ccl4, Ccl5, Tnfa, Gcsf, Cxcl1, Il1a, and Il3, were significantly induced upon B.1.351 infection in the lungs of hACE2 transgenic, BALB/c, and C57BL/6 mice." (PMID 34907154, 2021). "CCL5 was up-regulated by infection at 7 DPI although only at the highest MOI." (PMID 34805001, 2021). "CCL5 is a pro-inflammatory chemokine essential for T-cell activation and for directing the migration of immune cells such as T cells, monocytes, NK cells, and dendritic cells to sites of infection." (PMID 34519332, 2021). "Along with this observation, we also observed significantly lower levels of IL-6, IFN-γ, and CXCL-10 24 h post-infection, IL-17A and TNF-α 4 days post-infection, and IL-1β, CCL2 and CCL5 7 days post-infection in the lung of IL-38-treated mice, compared with mice without IL-38 administration." (PMID 33414457, 2021). "Interestingly, the infection with the H5N1 virus, a more pathogenic subtype, led to stronger CCL5 production in both cell types." (PMID 35126379, 2021). "CCL5 (RANTES), a pro-inflammatory chemokine associated with T-cell activation and recruitment to sites of inflammation is known to be upregulated in human survivors of EVD, even years after infection." (PMID 33806942, 2021). "CCR5 is the chemokine receptor for CCL5, but also the main infection route for the HIV." (PMID 33980589, 2021). "Infection with either virus led to enhanced expression of the inflammatory chemokines CCL5, CXCL10 and CXCL11, whereas mRNA expression levels of IL-6, IL-12 and IL-15 were only increased in MAYV-infected cells." (PMID 33799906, 2021). "Other ISGs were induced to a similar extent upon infection in all three cell lines, including CCL5." (PMID 32560274, 2020). "Interestingly, pre-incubation of RSV with LL-37 was noted to limit the expression of IL-6, CCL5, and IP-10 in response to infection." (PMID 32117246, 2020). "Importantly, CXCL10, CXCL9 and CCL5 were produced throughout the course of infection (until day 120), even when tissue parasitism was low." (PMID 32393333, 2020). "Moreover, genes such as Ifr9, Ifr8, Ifr7, CSF2RA, STAT1, and STAT2 were expressed to a greater extent in the PmQ infection group than PmCQ2, and Il22, Il6, Nos2, Ccl4, Ccl5, Ifr1, Socs1, and Socs3 were increased only in PmQ infected chickens rather than PmCQ2." (PMID 32851030, 2020). "Since CD8+ T cells may block HIV/SIV spread from cell- to-cell via CCR5-binding chemokines (i.e., MIP-1a/CCL3, MIP-1b/CCL4, and RANTES/CCL5), we also used viruses which were limited to a single cycle of infection." (PMID 32941545, 2020). "Later in infection sustained CCL5 production would likely drive maximal recruitment of the adaptive virus-specific T cell effectors that could clear virus." (PMID 32375993, 2020). "Il1β, Tnf, Il6, Ccl2, Ccl5, and Cxcl10 mRNAs were all increased in the CNS after infection." (PMID 32047134, 2020). "The chemokine genes (CCL3, CCL4 and CCL5) were also upregulated in these memory-like γδ T cells, which is similar to what had previously been reported to be upregulated in γδ T cells during an active infection." (PMID 33154754, 2020). "Notably, compared to “PAO1 alone,” pre-infection with IAV followed by PAO1 infection further increased IL-8, CCL-5, hBD-1, and elafin mRNA levels." (PMID 32117268, 2020). "Besides, mice sensitized with recombinant vaccinia expressing G-hRSV protein (rVV-G) showed a significant increase of both mRNA and protein levels for CCL5 during the first 24 h post-infection." (PMID 30936869, 2019). "In the current study, we showed trends toward increased baseline production of inflammatory cytokines TNF-α and CCL5/RANTES, hinting that chronic airway inflammation could contribute to defective antiviral responses upon infection observed in some patients." (PMID 31513433, 2019).
infection (continued). "Also, the inhibited CCL5 plays an essential role during inflammation by inducing the migration of blood leukocytes to sites of infection in order to initiate immune responses against invading pathogens." (PMID 31118097, 2019). "Also, a chemokine named RANTES (or CCL5) that is involved in T cell migration and immunity during infection was significantly reduced in male rats at 24 hours." (PMID 31612077, 2019). "Then, CCL5 is also increased in the second phase of hRSV infection at 168 h post-infection." (PMID 30936869, 2019). "For example, infection of human embryonic neural progenitor cells with JCPyV resulted in significant upregulation of the cytokines/chemokines such as CCL5/RANTES, GRO, CXCL1/GROα, CXCL16, CXCL8/IL-8, CXCL5/ENA78, and CXCL10/IP-10 and the chemokine receptor CXCR2." (PMID 31408949, 2019). "The infection was associated with limited immune cytokine/chemokine response activation; the highest increase of expression, following infection, was seen in CXCL-10 (IP-10), interleukin-6, 8, 12, and CCL5 (RANTES)." (PMID 29463209, 2018). "DOX treatment modulated CCL5, which is induced in the brain upon PbA infection." (PMID 29438386, 2018). "Recent extensive studies have indicated that microglia intrinsically produce CXCL10 and CCL5 upon infection with a variety of neurotropic viruses, including cytomegalovirus, human immunodeficiency virus, herpes simplex virus Theiler’s murine encephalomyelitis virus, and Japanese encephalitis virus." (PMID 30001342, 2018). "Regarding the chemokines, diverse studies in humans and mice have indicated that CXCL1, CXCL9, CXCL10, CCL2, CCL3, CCL4, and CCL5 are important in controlling the infection during the acute phase, and the levels of virtually all of them were increased in both BALB/c and C57BL/6 mice." (PMID 29662478, 2018). "In this study we show, that NK cells secrete chemokines such as CCL3/MIP-1α, CCL4/MIP-1β and CCL5/RANTES early on after stimulation with Aspergillus fumigatus and, in addition, adjust the concentration of chemokines released to the multiplicity of infection of Aspergillus fumigatus." (PMID 30563459, 2018). "Similar to the T. gondii data, both WT and P2X7R−/− mice had increased expression of epithelial CCL5 relative to naive mice following infection and CCL5 expression was significantly reduced in P2X7R−/− epithelial cells (10±3.3 in WT vs 4.5±4.0 in P2X7R−/−, P=0.042)." (PMID 27559003, 2017). "Similar to the in vitro data CCL5 was upregulated by infection (P<0.01)." (PMID 27559003, 2017). "Finally, CCL5 is a chemokine that attracts T cells eosinophils and basophils, and it recruits leukocytes to the site of infection." (PMID 28360908, 2017). "Secretions of IL-6 and CCL5 (RANTES) from infected cells were measured following infection." (PMID 28877226, 2017). "However, gene expression levels of IF1H1, OAS1, IFN-β, CXCL10 and CCL5 were increased in islets following infection with E16 and E30 compared to the mock-infected control." (PMID 28146100, 2017). "Similarly, in vivo, infection with either T. spiralis or T. gondii induced rapid upregulation of epithelial CCL5 in wild-type (wild-type (WT)) mice that was significantly reduced in P2X7R−/− littermate controls." (PMID 27559003, 2017). "Later in infection, at 6 days and onward, CCL5 is upregulated." (PMID 29194419, 2017). "But, infection of lentivirus containing the N-terminal fragment of iOPN could not increase or restore SeV-induced expression of IFN-β, CXCL10, Mx1 and CCL5 in WT and OPN-deficient macrophages, respectively." (PMID 27026194, 2016). "However, we observed that after infection the transcript levels of Ccl4 and Ccl5 were similarly up-regulated in the lungs of CAST/EiJ as for 129S1/SvImJ and C57BL/6J (data not shown)." (PMID 26921172, 2016).
infection (continued). "Moreover, an increased peri-follicular compartment also reflected an increased recruitment from the circulation, which matched the heightened levels of CCL5 and a number of other chemokines found after infection of the skin." (PMID 27160938, 2016). "Upregulation of its transcript in antigen-stimulated IgM+ plasma cells evokes the possibility that plasma cells-derived CCL5 could be important for alerting other immune cell partners about an infection." (PMID 27924814, 2016). "Examination of chemokine expression at memory showed that infection resulted in sustained upregulation of transcripts encoding for a variety of different chemokines, including CCL1, CCL2, CCL5, CCL8, CXCL9 and CXCL10 compared with control flank skin from the same animals." (PMID 27160938, 2016). "At the same time, activation by pathogen-associated molecular patterns (via Toll-like receptors, TLRs) leads to the release of more cytokines, such as PF-4 or CCL5 (RANTES) which leads to recruitment of circulating inflammatory cells and ensures a rapid response to infection." (PMID 25468720, 2015). "However, as we demonstrated, CC chemokines CCL3/MIP-1α, CCL4/MIP-1β, and CCL5/RANTES were unable to block infection by T-tropic isolates thus proving the specific and selective inhibition by CXCL12/SDF-1 for this type of viruses." (PMID 26097474, 2015). "The expression of late genes, IP10 and CCL5, was detected twelve hours post-infection." (PMID 25728279, 2015). "LY294002 potently inhibited CXCL8 and CCL5 production in response to infection with RV-1B or RV-16." (PMID 25541728, 2014). "Conversely, shortage of CCL5 in the serum of infected MC-deficient “sash” mutants was associated with reduced CD8 T-cell recruitment and consequently elevated virus replication and delayed clearance of productive infection." (PMID 24763809, 2014). "CCL5 levels were increased in Ncf1 mutant mice three days and 4 weeks after infection." (PMID 25188296, 2014). "However, in contrast to HBMECs, HBCAs secreted significantly more CCL5 in response to WNV-NY infection compared with WNV-MAD78 infection (P<0.005)." (PMID 24413421, 2014). "Despite the protective role of Met-CCL5 in the early days of infection, over 50% of Met-CCL5 treated adult mice still died after 19 days p.i., suggesting that additional treatment might be combined with Met-CCL5 to improve anti-RABV efficacy." (PMID 25182681, 2014). "TgCyp18 may also play a role with CCL5 in the migration of macrophages to the site of infection, and with CCL2 and CXCL10 in the transport of T. gondii-infected cells to the liver." (PMID 24661782, 2014). "CCL5 recruits macrophages, dendritic cells, basophils, eosinophils, mast cells, natural killer cells, and T lymphocytes to sites of inflammation and infection where they either participate in resolving inflammation or provide cues for activation of the adaptive immune response." (PMID 24025197, 2013). "Three months before the discovery of CXCR4 as a co-receptor for HIV, it had been reported that CCL3L1 (MIP-1αP), CCL4 (MIP-1β) and CCL5 (RANTES) could block infection." (PMID 23692808, 2013). "Levels of mRNAs for CCL5 remained stable following infections with both isolates." (PMID 23265239, 2013). "However, at 11 weeks of infection, when lesions were significantly different, we found higher expression of CCL5 and CCL2 mRNA and, at 20 weeks afterinfection, we found higher concentrations of CCL5 and CCL2 protein in lesions." (PMID 22203861, 2012). "CCL5 mRNA transcription is induced by infection with UV irradiated HCMV that can be inhibited by expression of the IE86 immediate early protein following productive infection." (PMID 23202490, 2012). "This high expression of CCL5 in immunotherapy group might be enhancing the T cell recruitment at the site of infection." (PMID 22844392, 2012).